METTL15P1 (methyltransferase like 15 pseudogene 1)
Description:
Probable S-adenosyl-L-methionine-dependent methyltransferase.
Synonyms: formerly METT5D2
Gene: Transcribed processed pseudogene on chromosome 3 (156,713,884 to 156,714,928, reverse strand). Ensembl gene ENSG00000174912.